IL31 (interleukin 31)
Diseases named in the same sentence as IL31 in open-access papers (continued):
Sharing a sentence is not in itself a finding about the gene and the disease.
asthma (continued). "In the present study, it was hypothesised that the upregulation of IL-31 expression is more pronounced in more severe forms of asthma." (PMID 26956917, 2016). "Furthermore, since lower levels of 25(OH) Vit D and high levels of IL-31 and IL-33 are associated with Th2 immunity of allergic disease, we hypothesized a potential interaction between these markers and clinical and functional parameters in asthma and rhinitis." (PMID 25061262, 2014). "Although our finding suggest that IL-31 may be useful indicator for asthma, future studies with larger sample sizes as well as animal experiments and in vitro experiments should be performed to determine whether IL-31 can be used as a potential drug target for treating asthmatic patients." (PMID 26956917, 2016). "For the emergence of allergic inflammation, such as in asthma, activating the IL-33/ST2-involving Th2/IL-31 immune response is particularly important." (PMID 36341243, 2022). "Moreover, perspective studies will also be required to determine whether IL-31 levels are stable or increase during exacerbations of asthma and whether the levels of IL-31 would decline when those exacerbation subjects are completely controlled after treatments." (PMID 26956917, 2016). "Levels of IL-31 in the serum, bronchoalveolar lavage fluid (BALF) and bronchial tissue of mild-to-moderate and severe asthma patients were determined and compared to those of healthy controls." (PMID 26956917, 2016). "Serum IL-31 levels correlated positively with Th2 related cytokines (IL-5, IL-13, and TSLP), asthma severity or total serum immunoglobulin E (IgE), and inversely with asthma control and the forced expiratory volume in 1 second (FEV1)." (PMID 26956917, 2016). "Expressions of IL-31 and IL-31 receptor (IL-31RA and OSMR) were more prominent in the bronchial tissue in severe compared to mild asthma and controls." (PMID 26956917, 2016). "The present study showed that IL-31 does not influence the evolution of pre-existing asthma conditions in the absence of allergic inflammation." (PMID 38397331, 2024). "Considering IL-31 is the only known activator of IL-31RA, future studies are warranted to determine the molecular identity of mediator(s) that activate IL-31RA to alter the contractile functions of ASMC and AHR in asthma." (PMID 38081868, 2023). "Consistent with dominant role for IL-31RA but not IL-31 in asthma pathogenesis in these models, IL-31RA was elevated in wildtype mice exposed to allergens and in human lung tissues obtained from asthmatics." (PMID 38081868, 2023). "In the present study, children had wheezing or recurrent wheezing but not asthma, so we might speculate that IL-31 may play a role when allergic, eosinophilic inflammation is already settled, without having a role in preventing its development." (PMID 38397331, 2024). "It was also examined whether or not correlations exist between IL-31 expression and disease severity (e.g., lung function, asthma control)." (PMID 26956917, 2016). "However, there are no studies investigating the expression pattern of IL-31 in patients with asthma of varying severity in a clinical setting." (PMID 26956917, 2016).
prurigo nodularis (21 papers, 2013 to 2026). Prurigonodularis (PN) is a skin disease in which hard crusty lumps are formed on the skin that itches intensely. "IL-31, a cytokine associated with itching and the pathophysiology of prurigo nodularis, is crucial in T-helper 2 skin inflammation by promoting the production of IL-4 and IL-13." (PMID 41110231, 2025). "IL-31, a cytokine strongly linked to pruritus and inflammation, is known to stimulate cutaneous nerve fibers and drive neuroimmune activation in prurigo nodularis (PN) patients." (PMID 41268562, 2025). "IL-31 may also play a role in the sensation of itch, because several itch-associated skin diseases like prurigo nodularis, chronic spontaneous urticaria, and allergic contact dermatitis exhibit high levels of IL-31." (PMID 23531535, 2013). "In prurigo nodularis (PN), barrier compromise is largely secondary to mechanical injury, but neural dysregulation is prominent; IL-31-sensitive itch–scratch loops perpetuate nodular lesions atop a Th2 milieu." (PMID 41226755, 2025). "The present findings support the use of nemolizumab as an effective and safe treatment option for prurigo nodularis, aligning with previous research on biologics targeting the IL-31 pathway." (PMID 41110231, 2025). "In a study that compared the skin biopsies from patients with prurigo nodularis and healthy skin, it is demonstrated that high IL-31 levels were detected in the skin of prurigo patients." (PMID 39487054, 2025). "Elevated levels of IL-31 have been observed in pruritic skin diseases, such as prurigo nodularis, AD, bullous pemphigoid, cutaneous T-cell lymphoma, and PSO." (PMID 37834183, 2023). "Vixarelimab is a monoclonal antibody being developed for the treatment pf prurigo nodularis by Kiniksa Pharmaceuticals Corp; it simultaneously targets both the OSMRβ, which mediates signaling of IL-31, and the oncostatin M pathways." (PMID 33644103, 2021). "Targeting the elements of the IL-31 pathway may be beneficial for treating intractable itch in AD and other pruritic diseases, such as prurigo nodularis, either as a mono or combined therapy." (PMID 36839897, 2023). "An analysis of skin samples from patients with various chronic inflammatory skin diseases revealed that the highest levels of IL-31 were located in lesional skin from individuals with prurigo nodularis, with an elevation of IL-31 mRNA almost 50-fold higher than that of skin from healthy individuals." (PMID 33644103, 2021).
allergic asthma (17 papers, 2014 to 2024). A asthma with a basis in a pathological type I hypersensitivity reaction. "IL-31 is a Th2-related cytokine implicated in tissue remodeling in chronic lung and skin diseases, including allergic asthma, atopic dermatitis (AD), fibrosis, and itch-associated conditions." (PMID 38081868, 2023). "Relevant studies have suggested that IL-31 may be involved in supporting allergic inflammation and is associated with a specific airway epithelial cell response that may characterize allergic asthma." (PMID 38397331, 2024). "In this study, we investigated the pathophysiological role of the IL-31/IL-31RA axis using two complementary mouse models of allergic asthma." (PMID 38081868, 2023). "More recently, enhanced IL‐31 serum levels have also been observed in patients with allergic rhinitis and allergic asthma." (PMID 32648940, 2021). "Previous studies also indicated increased expression of IL31 in allergic asthma and allergic rhinitis." (PMID 32317758, 2020). "In summary, we first demonstrated that IL-31 promoted lung inflammation in allergic asthma mice via inducing production of chemokines in alveolar epithelial cells to recruit cell infiltrates." (PMID 30647024, 2019). "Data concerning the high serum levels of IL-33 and IL-31 levels were also gained from patients affected by the combination of allergic asthma and rhinitis." (PMID 31766607, 2019). "In fact, they found significant correlations between plasmatic components of the IL-33/ST2 axis and IL-31 in both allergic rhinitis patients and those with concomitant allergic asthma." (PMID 31766607, 2019). "In an attempt to further understand the role of IL-31 in modulating airway inflammation, we investigated the dynamic levels of IL-31 in a mouse model of allergic asthma, as well as the effect of IL-31 on lung alveolar epithelial cells." (PMID 30647024, 2019). "The present study aims to investigate the plasma levels of 25(OH) Vit D, IL-31, and IL-33 in children with allergic asthma and rhinitis." (PMID 25061262, 2014). "25-Hydroxyvitamin D [25(OH) Vit D], IL-31, and IL-33 plasma levels were measured in 28 controls (HC), 11 allergic rhinitis (AR) patients, and 35 allergic asthma with rhinitis (AAR) patients." (PMID 25061262, 2014). "However, the role of the IL-31-IL-31RA axis in the induction of AHR or airway inflammation during allergic asthma remains unexplored." (PMID 38081868, 2023). "More recently IL-31 was found at increased levels in sera of patients with allergic asthma." (PMID 30647024, 2019). "One explanation is that IL-31 is one of these Th2-type cytokines that induce inflammation-related cytokines, such as IL-4, IL-5 and IL-13, which form the complex network of cytokines that governs the development allergic asthma and so that role of IL-31 may be covered by other stronger cytokines." (PMID 30647024, 2019). "Here, we report a significant increase in the expression of IL-31RA, but not its cognate ligand IL-31, in mouse models of allergic asthma." (PMID 38081868, 2023). "We observed a significant increase in the expression of IL-31RA, but not its cognate ligand IL-31 during allergic asthma." (PMID 36824812, 2023). "As such, the regulation of IL31 may in part explain the Th2 skewing we observed in the WNT5A transgenic mouse and support a potential role for WNT5A in Th2 type inflammation and allergic asthma." (PMID 32317758, 2020). "Although the hypothesis tested in this study was straightforward, it was surprising that IL-31RA, but not the Th2 T cell-derived cytokine, IL-31 was responsible for inducing AHR in allergic asthma." (PMID 38081868, 2023). "However, anti-IL-31 antibodies did not neutralize the production of Th2 type cytokines either in vitro or in vivo mouse models of allergic asthma." (PMID 30647024, 2019). "Here, we provide evidence that both Th1 and Th2 cytokines (IFNγ, IL-4, and IL-13) upregulate IL-31RA but not IL-31 in SMC and lungs during allergic asthma." (PMID 38081868, 2023).
allergic asthma (continued). "However, we observed no significant increase in IL-31 levels in the lungs during HDM- and SEA-induced allergic asthma." (PMID 38081868, 2023).
allergic disease (17 papers, 2012 to 2025). An immune response that occurs following re-exposure to an innocuous antigen, and that requires the presence of existing antibodies against that antigen. "We investigated whether low vitamin D is linked with circulating IL-31 and IL-33 in children with allergic disease of the airways." (PMID 25061262, 2014). "In this scenario, we are able to hypothesize that IL-31 and the related IL-33 activity might be linked with vitamin D in allergic disease." (PMID 25061262, 2014). "IL-31 and IL-33 correlate with Th2-associated cytokines in allergic disease." (PMID 25061262, 2014). "VD also seems to have a role in allergic diseases and bone pathologies mediated by Th2 cells, via the IL-31/IL-33 axis, which is another new area to investigate the intricate overlapping mechanisms that connect allergies and osteoporosis." (PMID 36009422, 2022). "The proliferation of Th2 cells leads to an increase in interleukin 31 (IL-31) synthesis, an effector cytokine that plays an important role in the pathogenesis of atopic and allergic diseases." (PMID 34440059, 2021). "The two Th2 cytokines IL-31 and IL-33 demonstrated to be relevant in the pathogenesis of both allergy and osteoporosis as well as autophagy and these too have been suggested as potential therapeutic target." (PMID 31973226, 2020). "Furthermore, these studies suggest that IL-31, in addition to its pruritic actions, also has potential immunomodulatory roles in terms of supporting Th2-type immunity, which often underpins IgE-associated autoimmune diseases (such as bullous pemphigoid and urticaria) as well as allergies." (PMID 31281316, 2019). "Interleukin 31 (IL-31) is a novel T helper type 2 effector cytokine that plays an important role in the pathogenesis of allergic diseases." (PMID 26956917, 2016). "Interleukin-31 (IL-31) has also been reported to be involved in Th2 mediated diseases such as allergic diseases." (PMID 25122210, 2014). "The present study investigated for the first time the relationship between IL-31, IL-33, and 25(OH) Vit D in pediatric allergic disease of the airways." (PMID 25061262, 2014). "Interleukin 31 (IL-31) is a T helper type 2 effector cytokine that plays an important role in the pathogenesis of atopic and allergic diseases." (PMID 25061262, 2014). "IL-31 signals act through a receptor composed of IL-31 receptor A and oncostatin M receptor promoting the cell activation during allergic diseases." (PMID 25061262, 2014). "Recent studies also suggest a role of IL-31 in the pathogenesis of other allergic diseases including allergic rhinitis." (PMID 22853438, 2012). "Recently was suggested that the IL-31/IL-33 axis could be involved in different conditions such as cancer, autoimmune diseases and allergies." (PMID 31973226, 2020). "Our findings showed that IL-31 expression is higher in KD patients after IVIG treatment and may be the cause of increases in allergic diseases." (PMID 25122210, 2014). "Thus, this led to the newest theory of an “IL-31/IL-33 axis” that could be involved in several conditions such as allergies, autoimmune-diseases, and cancer." (PMID 31766607, 2019). "IL-31 frequently activates JAK2-STAT3 signaling, promoting inflammation and allergic diseases, such as asthma and dermatitis." (PMID 32528891, 2020).
autoimmune disease (14 papers, 2016 to 2025). A disorder resulting from loss of function or tissue destruction of an organ or multiple organs, arising from humoral or cellular immune responses of the individual to their own tissue constituents. "Decreased 1,25-dihydroxycholecalciferol [1,25(OH)2D] and upregulated IL-33/IL-31 axis can alter the balance between inflammatory Th1/Th17 cells and T regulatory (Treg) cells and promote the bacterial translocation, associated with the pathophysiological processes of autoimmune diseases like IBD." (PMID 39758314, 2024). "The fact that IL‐31 is not only elevated in pruritic skin diseases but also in autoimmune diseases suggests that it plays an important role in inflammatory responses and autoimmunity beyond itch." (PMID 37632245, 2023). "To summarize, our review shows that the IL-31/IL-33 axis represents a potential pathway of inflammation in allergic and autoimmune diseases." (PMID 31766607, 2019). "In this review, we discuss some of the latest discoveries regarding IL-31 and IL-33 among allergic and autoimmune diseases." (PMID 31766607, 2019). "Another significantly increased cytokine, IL-31, is not reported to be associated with any autoimmune disease, including IgAN." (PMID 36902810, 2023). "However, the input of other IL-31-producing cells, especially CD4+ T cells, in these autoimmune diseases still needs to be elucidated in terms of IL-31-mediated immunomodulatory roles." (PMID 31281316, 2019). "Furthermore, they found in serum the positive and close correlation between IL-31 and autoimmune diseases like multiple sclerosis." (PMID 29713240, 2018). "Here we evaluated the role of Interleukin-31 (IL31), a protein belonging to the pro-inflammatory IL-6 cytokine family which has been characterized in autoimmune disease, in tumorigenesis." (PMID 28147314, 2017). "In lupus erythematosus there is currently only sparse evidence to suggest a role of IL-31 and, as yet, no reports specifically dealing with cutaneous forms of this autoimmune disease." (PMID 31281316, 2019).
cutaneous T-cell lymphoma (14 papers, 2016 to 2024). "The pathogenesis of UP is not well elucidated, but studies have implicated interleukin-31 (IL-31), which is upregulated by Th2 cells in pruritic disorders such as AD and cutaneous T-cell lymphoma." (PMID 31261951, 2019). "Early on IL-31 expression and serum levels have been investigated in patients suffering from cutaneous T cell lymphoma." (PMID 33644104, 2021). "Interleukin-31 seems to be a main itch mediator in several hematologic disease such as Cutaneous T cells lymphomas." (PMID 34118946, 2021). "It has been shown that IL-31 serum levels are increased in patients with cutaneous T cell lymphoma and, more recently, our group has demonstrated that the IL-31/IL-31R axis promotes tumor growth in Follicular B cell lymphoma." (PMID 29156718, 2017). "Notably, an increasing body of literature links IL-31 with malignant diseases such as endometrial carcinoma, lung cancer, myeloproliferative disorders, mastocytosis, cutaneous T cell lymphoma and follicular B cell lymphoma." (PMID 33644104, 2021).
inflammatory skin disease (11 papers, 2013 to 2025). Inflammatory skin disorders covers a broad category that includes many conditions ranging in severity, from mild itching to grave medical health complications These disorders are common in people of all ages and races. "In conclusion, IL-31 plays an important role in several inflammatory skin diseases, and treatment targeting IL-31 is expected to contribute meaningfully to the clinical management of a wide range of diseases." (PMID 33644103, 2021). "IL-31 is also known to promote skin inflammatory disorders in mouse models and in the human setting." (PMID 33763080, 2021). "This indicates that IL-31 plays a role in the orchestration and accumulation of basophils in inflammatory skin diseases such as CsU." (PMID 31281316, 2019). "By blocking IL-31 signaling, nemolizumab may disrupt T cell immune balance, potentially triggering inflammatory skin disorders such as bullous pemphigoid, urticaria, and psoriasiform dermatitis." (PMID 40104458, 2025). "T helper 2 (Th2)-mediated dermatoses are inflammatory skin diseases driven by CD4+ Th2 cells that produce interleukin (IL)-4, IL-5, IL-13, and IL-31, promoting immunoglobulin E (IgE) class switching, eosinophil recruitment, mast cell degranulation, and pruritus." (PMID 41226755, 2025). "There are various neuropeptides involved in inflammatory skin disorders, which include substance P (SP), calcitonin gene-related peptide (CGRP), brain-derived neurotrophic factor (BDNF), corticotropin-releasing factor (CRF) and interleukin 31 (IL-31)." (PMID 23108364, 2013).
mastocytosis (10 papers, 2016 to 2025). A clonal myeloproliferative neoplasm characterized by the proliferation and accumulation of neoplastic mast cells in one or multiple organs or organ systems. "In mastocytosis, IL-31 is directly associated with the activation of the IL-31R receptor in neurons, increasing the intense itching experienced by patients with these diseases." (PMID 41009465, 2025). "Further studies are needed to validate the use of IL-31 levels as a diagnostic marker in patients with mastocytosis, particularly in those with osteosclerosis and advanced or smoldering SM." (PMID 37108232, 2023). "Authors analyzed association of mastocytosis with two variants in promoter IL31 gene (−1066 G > A (rs 11608363), −2057 G > A (rs 6489188), and one in intronic region (IVS2 + 12A > G) and found that −2057AA genotype is associated with a high prevalence of mastocytosis (CM and SM) in adult patients." (PMID 33401724, 2021). "In mastocytosis, the dysregulated production of IL-4, IL-31, and other cytokines exacerbates the disease’s severity and perpetuates a cycle of mast cell activation, immune response, and symptom manifestation." (PMID 41009465, 2025). "MC can secrete IL-31, a well-known pruritogenic mediator, and circulating levels can be increased in mastocytosis and correlate with disease severity, especially intensity of pruritus, tryptase levels, osteosclerosis, and extent of BM infiltration by MC." (PMID 37108232, 2023). "In addition, IL-31 also plays a role in TH2-driven and autoimmune diseases such as contact dermatitis, urticaria, mastocytosis, allergic rhinitis; but also systemic sclerosis, dermatomyositis, and lupus erythematosus." (PMID 33644104, 2021).